KPNA1 (karyopherin subunit alpha 1)
Diseases named in the same sentence as KPNA1 in open-access papers (continued):
Sharing a sentence is not in itself a finding about the gene and the disease.
infection (11 papers, 2011 to 2025). The state of being infected such as from the introduction of a foreign agent such as serum, vaccine, antigenic substance or organism. "The mechanism of viral 2B protein to assist EV-A71 to evade the type I IFN-mediated broad-spectrum antiviral effects through promoting KPNA1 degradation, probably via its N-terminal H1 domain, is one of many strategies used by EV-A71 during its infection." (PMID 34992585, 2021). "The phosphorylated and un-phosphorylated STAT3 competed with STAT1 for binding to the decreased KPNA1 post infection and repressed downstream ISG expression." (PMID 31575039, 2019). "Our present study demonstrated that translocation of activated STAT1 and STAT3 induced by EV71 infection required KPNA1 in T98G cells, and consistent with a previous study in RD cells, we observed degradation of KPNA1 in T98G cells upon infection." (PMID 31575039, 2019). "Enterovirus 71 (EV71) infection suppresses IFN responses by inhibiting STAT1/2 nuclear transport through the induction of caspase-3-dependent degradation of KPNA1." (PMID 29370303, 2018). "Additionally, ferret infection with SARS-CoV-2 showed an increase in KPNA1, KPNA4, and KPNA5 expression (p = 0.0473, p = 0.0449, and p = 0.0371, respectively) when compared with the mock treatment." (PMID 34696514, 2021). "Intriguingly, we found that besides the degradation of KPNA1, another indispensable factor that restricts host antiviral response was the competitive binding of STAT3 to KPNA1 during infection." (PMID 31575039, 2019). "Interestingly we detected another family of nuclear transporter KPNA1, KPNA2, and KPNA4 to be significantly decreased at the later time point of infection." (PMID 34006825, 2021). "In addition, the expression levels of KPNB1, KPNA1, KPNA2, KPNA4, KPNA6, and KPNA7 changed with the infection time of the three strains while KPNA3 and KPNA5 did not change with the incubation time." (PMID 40687856, 2025).
cancer (7 papers, 2007 to 2025). A tumor composed of atypical neoplastic, often pleomorphic cells that invade other tissues. "In detail, although KPNA1 (a nuclear import protein) is overexpressed in several cancers, it was found downregulated in AML bone marrow cells in this study, contradicting previous reports." (PMID 39940906, 2025). "Our analysis confirmed that the number of KPNA1-positive cells, corresponding pathological scores and staining intensity of KPNA1 were obviously lower in cancer tissues compared with normal tissues." (PMID 35991835, 2022). "In addition, the central roles of KPNA1 ~ 7 in the malignant progression of other cancers were increasingly being recognized." (PMID 37501099, 2023). "Therefore, it would be interesting to investigate the role of STAT1 and STAT2 as well as KPNA1 in radiation-increased KPNB1-mediated IRF1 expression in these cancers." (PMID 34069326, 2021). "In starved culture medium with 0.1% FBS, HaCaT cell growth was significantly suppressed by siRNA knockdown of KPNA1, 2, 3, and 4, suggesting adequate expression of KPNAs may be required for growth maintenance, especially in starved cells such as cancer cells." (PMID 24098495, 2013). "The percentage of KPNA1-positive cells and the relative intensity in Grade III cancer tissues were markedly lower than those in Grade I and II tissues." (PMID 35991835, 2022). "We validated the knockdown effect of each KPNA (KPNA1, KPNA5, and KPNA6) on the interactions between endogenous PHB2 and nuclear ERα in BIG3-depleted cancer cells." (PMID 26052702, 2015). "The results showed that the depletion of only BIG3 led to interactions between endogenous PHB2 released from BIG3 with nuclear ERα but that the depletion of BIG3 and KPNA1, KPNA5, and KPNA6 did not, indicating that PHB2 binding to nuclear ERα in cancer cells is KPNA-mediated." (PMID 26052702, 2015).
psychiatric disorder (4 papers, 2021 to 2025). A disorder characterized by behavioral and/or psychological abnormalities, often accompanied by physical symptoms. "The elevated KPNA1 expression in neurons and the correlation between mutations and psychiatric disorders suggest its broader significance beyond nucleocytoplasmic transport." (PMID 40010609, 2025). "Mutated KPNA1, which has been shown to be associated with psychiatric disorders (KPNA1E448X), was predominantly localized to the nucleus and lost from the axon." (PMID 40010609, 2025). "Our findings demonstrate that Kpna1 deletion can trigger widespread behavioral abnormalities associated with psychiatric disorders, some of which were further exacerbated by exposure to adolescent social isolation." (PMID 34767585, 2021). "Our study expands on these previous reports by providing novel evidence that genetic alterations in Kpna1 can combine with environmental stress factors to cause behavioral abnormalities associated with several psychiatric disorders." (PMID 34767585, 2021). "Our findings demonstrate that Kpna1-deficient mice may be useful as a G × E interaction mouse model for psychiatric disorders and for further investigation into the pathogenesis of such diseases and disorders." (PMID 38336912, 2024). "Our findings indicate that Kpna1-deficient mice may be valuable as a G × E interaction mouse model for psychiatric disorders and for further investigation into the pathogenesis of such diseases and disorders." (PMID 38336912, 2024). "Thus, KPNA1 may contribute to psychiatric disorders, however its causal roles and relevant molecular and cellular mechanisms remains elusive." (PMID 38336912, 2024). "Characterization of group-housed and isolated Kpna1 KO mice using a behavioral test battery showed that Kpna1 deletion and social isolation stress both significantly alter several different psychiatric disorder-related behaviors." (PMID 34767585, 2021). "In this study, we aimed to further characterize the physiological roles of KPNA1 in the brain by using an extensive behavioral test battery to analyze psychiatric disorder-related behaviors in a previously established Kpna1 KO mouse line." (PMID 34767585, 2021). "In this study, we investigated the effects of Kpna1 deletion and social isolation stress on psychiatric disorder-related behaviors by exposing group-housed and isolated Kpna1 KO mice to an extensive behavioral test battery." (PMID 34767585, 2021). "Although KPNA1 is localized in the neurites of neurons, its role in axonal transport mechanisms remains unclear, and data on the connection between psychiatric disorders and signaling at the periphery of neurons remain limited." (PMID 40010609, 2025). "Behavioral analyses were conducted to determine whether genetic disruption of Kpna1 and/or the subchronic administration of PCP affect psychiatric disorder-associated behaviors." (PMID 38336912, 2024). "The use of Kpna1 knockout mice as a model for psychiatric disorders may show promise for further investigation of gene-environment interactions involved in the pathogenesis of psychiatric disorders." (PMID 34767585, 2021). "Finally, the finding that social isolation stress in Kpna1 KO mice resulted in an augmentation of some behavioral alterations demonstrates the effectiveness of this mouse models to dissect the interactive effects of individual genetic and environmental factors in relation to psychiatric disorders." (PMID 34767585, 2021).
tumor (4 papers, 2008 to 2024). "The expression levels of KPNA1 and KPNA2 were significantly associated with the tumor histologic grade." (PMID 35991835, 2022). "Although most of the tumor samples were Grade II, the smallest proportion and weakest intesity for KPNA1 immunostaining were observed in the Grade III samples." (PMID 35991835, 2022). "Moreover, the deeper mechanism by which KPNA1 inhibits tumor cell proliferation needs to be further studied in the future." (PMID 35991835, 2022). "The weakest KPNA1 expression and strongest staining for KPNA2 were observed in grade III tumor tissue." (PMID 35991835, 2022). "The expression of KPNA1 and KPNA2 in the tumor tissues (n = 106) and adjacent tissues was detected by immunohistochemistry." (PMID 35991835, 2022). "This may be the reason for the opposite trends in KPNA1 and KPNA2 expression in the same tumor cell line." (PMID 35991835, 2022).
KPNA1 also shares sentences with these, for which no sentence is quoted: viral infection (2 papers); autism (1); breast tumour (1); COVID-19 (1); depression (1); Enteroviral infection (1); hepatocellular carcinoma (1); Huntington disease (1); neurological disorders (1); Parkinson disease (1); prostate carcinoma (1); Sepsis (1).